ALB (albumin)
Diseases named in the same sentence as ALB in open-access papers (continued):
Sharing a sentence is not in itself a finding about the gene and the disease.
malnutrition (2,239 papers, 2003 to 2026). Inadequate nutrition resulting from poor diet, malabsorption, or abnormal nutrient distribution. "Although albumin cannot be considered a causal factor, its association with mortality likely reflects a composite of malnutrition, inflammation, impaired metabolic reserve, and increased susceptibility to both cardiovascular and infectious complications." (PMID 41517580, 2026). "Reduced albumin reflects impaired hepatic synthesis, malnutrition, and systemic disease, and is linked with advanced fibrosis and poor prognosis in metabolic dysfunction-associated steatotic liver disease (MASLD)." (PMID 41601806, 2026). "HF patients often suffer from malnutrition or cardiac cachexia, which is associated with loss of muscle mass and proteins, including albumin." (PMID 40077630, 2025). "Serum ALB, a critical marker of nutritional status in patients with gastrointestinal cancers, is closely linked to malnutrition when its levels are low." (PMID 41311550, 2025). "Albumin reflects protein reserve and exerts antioxidant and anti-inflammatory functions, with low levels indicating malnutrition and systemic inflammation that are linked to poor pneumonia outcomes." (PMID 41170357, 2025). "First, malnutrition, as indicated by low serum albumin, is associated with reduced hepatic protein synthesis and has been linked to lower RBP4 levels." (PMID 40881125, 2025). "Our findings revealed a substantial burden of these conditions, with 33.0% of participants exhibiting hypoalbuminemia (serum albumin <35 g/L) and 73.5% at risk of or experiencing malnutrition (MNA-SF score < 12)." (PMID 41536828, 2025). "Patients categorized as high-risk for malnutrition showed significantly lower levels of serum albumin and triglycerides and higher HDL-C levels compared with their counterparts." (PMID 40870441, 2025). "Albumin is the most used plasma biomarker for assessing malnutrition and hypoalbuminemia has been associated to low muscle mass and function, increased mortality risk, and poor recovery outcomes both in community-dwelling and hospitalized older adults." (PMID 41340658, 2025). "Relative to the GNRI grouping variable, albumin concentrations increase as the risk of malnutrition decreases." (PMID 40094974, 2025). "Studies have linked lower serum albumin levels and malnutrition to worse outcomes in coronary heart disease, including higher risks of acute heart failure and cardiogenic shock in ACS patients." (PMID 40777566, 2025). "Geriatric nutritional risk index, a combined marker of body mass index and serum albumin level, is a marker of malnutrition that is easily calculated, enables serial evaluation, and is a powerful indicator of mortality in these patients." (PMID 39873869, 2025). "Recent studies have shown that reduced serum albumin levels are linked to systemic inflammation activation and an increased risk of malnutrition." (PMID 40386214, 2025). "Low ALB levels, reflecting systemic inflammation or malnutrition, are associated with reduced IFX exposure and poorer clinical outcomes." (PMID 41438746, 2025). "Yet, to our knowledge, no prior research has examined the potential moderating influence of albumin levels on the association between CC and malnutrition diagnosis." (PMID 41440732, 2025). "Although the role of ALB in the assessment of nutritional status has been challenged recently, studies have shown that patients with low ALB levels are at risk of malnutrition." (PMID 40406156, 2025). "A prospective study involving 2,465 patients in Switzerland revealed that elevated C-reactive protein and increased malnutrition risk were associated with low serum albumin levels." (PMID 40168268, 2025). "Statins can be discontinued in very frail AM patients who have low serum cholesterol and low albumin levels due to malnutrition, low atherosclerotic cardiovascular disease (ASCVD) risk and short life expectancy." (PMID 40863223, 2025).
malnutrition (continued). "Low serum albumin levels were linked to all-cause and also to cardiovascular mortality, emphasizing the role of malnutrition and inflammation in the outcome of HD patients." (PMID 40136613, 2025). "In cancer patients, the relationship between albumin as a standalone indicator of malnutrition and prognosis and the association between various malnutrition indices and prognosis have been demonstrated in the literature." (PMID 40004836, 2025). "Low levels of albumin are often associated with chronic inflammation, cancer, liver disease, kidney disease syndrome, and malnutrition, which are all systemic diseases." (PMID 41480543, 2025). "Low albumin levels typically indicate malnutrition and inflammation, which are also linked to dyslipidemia and higher TG/HDL-C ratios." (PMID 41283273, 2025). "Malnutrition risk was assessed using the GNRI ([1.489 × serum albumin g/L] + [41.7 × current/ideal body weight])." (PMID 41408535, 2025). "As a result of SBS, the patient experienced severe diarrhea, weight loss (BMI: 19 kg/m2), and malnutrition, demonstrated by low albumin (26 g/L) and pre-albumin (0.12 g/L) levels." (PMID 40098817, 2025). "There is evidence to indicate that reduction of albumin is associated with infection, systemic inflammation, malnutrition and frailty." (PMID 40168268, 2025). "Based on data from training and validation queues, this study reveals that BMI, HGS, FFM, MUAC, and albumin are independent risk factors associated with malnutrition in older adult HF patients." (PMID 40521364, 2025). "Albumin, a key indicator of nutritional status, has been implicated in the pathogenesis of ED due to its association with malnutrition." (PMID 40099259, 2025). "A higher UCR has been associated with decreased serum albumin, body mass index and waist circumference, and it has also been suggested as an index of malnutrition." (PMID 40583865, 2025). "Deficient vitamin D3 levels and albumin levels are not only risk markers for malnutrition but also prevalent in kidney diseases, which constitute a high risk for general health." (PMID 40863037, 2025). "The clinical indicators commonly associated with malnutrition in cancer patients include albumin and hemoglobin levels, and albumin can serve as a sensitive marker for evaluating nutritional status." (PMID 40271430, 2025). "We reported a significant association between patients at high risk of malnutrition (defined by a MUST score ≥1 or albumin levels <35 mg/dL) before surgery and a greater decrease in hemoglobin (i.e., anemia) in early PODs." (PMID 40458822, 2025). "Inflammation, which is also a prominent factor in malnutrition, is associated with a higher fractional catabolic rate and a decreased synthesis rate of albumin." (PMID 39446306, 2025). "Conversely, serum albumin, a marker of nutritional status, is associated with better outcomes in cancer patients, as low albumin levels often reflect malnutrition and systemic inflammation." (PMID 40709341, 2025). "ALB serves as a key biomarker for nutritional status and chronic inflammatory states, with reduced levels commonly linked to chronic pathologies and malnutrition." (PMID 40809897, 2025). "Reduced albumin levels are typically associated with chronic inflammation and malnutrition, which can exacerbate inflammatory responses and increase the risk of depression." (PMID 40182647, 2025). "While our finding of a protective association for albumin aligns with literature suggesting that malnutrition or systemic inflammation (for which low albumin is a marker) can increase infection susceptibility, contradictory evidence exists." (PMID 41293740, 2025). "Serum albumin: Hypoalbuminemia (<2.5 g/dL) is consistently associated with poor outcomes, indicating severe malnutrition." (PMID 40077775, 2025). "Lower levels of ALB often indicate underlying conditions such as malnutrition or an inflammatory state, both of which are recognized risk factors for DVT." (PMID 39982917, 2025).
malnutrition (continued). "Possible causes of a drop in patients’ albumin include liver failure, kidney disease, heart failure, gastrointestinal conditions, and malnutrition." (PMID 40573280, 2025). "Inflammatory responses in ICH involve both neutrophils and albumin, and hypoalbuminemia, often seen in malnutrition, renal or hepatic issues, is linked to poorer health outcomes and greater frailty." (PMID 39935611, 2025). "Studies demonstrate a significant association between low albumin levels and both chronic inflammation and malnutrition." (PMID 41479660, 2025). "Low albumin levels often indicate malnutrition, while patients’ nutriture is associated with disease activity, and the nutriture of active IBD patients is worse." (PMID 40046919, 2025). "In this study, low serum albumin (< 40.5 g/L) and hemoglobin levels (< 105 g/L) on admission were significantly associated with malnutrition in patients with CAP." (PMID 40370727, 2025). "The GNRI, which combines BMI and serum albumin levels to predict the risk of malnutrition, is another indicator designed to evaluate the nutritional status of geriatric individuals." (PMID 40566551, 2025). "Their findings indicated that low serum albumin levels and severe malnutrition were strongly associated with reduced survival." (PMID 40077775, 2025). "Second, chronic low albumin levels indicate prolonged protein deficiency and malnutrition, which can weaken bone formation by reducing collagen production and IGF-1 availability – key factors for bone strength." (PMID 40297171, 2025). "Low albumin levels are linked to an increased risk of malnutrition, reduced OS, and elevated inflammatory markers such as interleukin-6 and C-reactive protein." (PMID 40678069, 2025). "Key biochemical markers—such as low serum albumin, prealbumin, hemoglobin, total cholesterol, and vitamin D levels, as well as elevated C-reactive protein—are critical indicators of malnutrition risk." (PMID 40704314, 2025). "In older adult HF patients, BMI, grip strength, FFM, MUAC and albumin are identified as independent risk factors for malnutrition." (PMID 40521364, 2025). "The logistic analyses revealed that body mass index (BMI), grip strength, mid-upper arm circumference (MUAC), fat-free mass (FFM), and albumin independently serve as risk factors of malnutrition in older adult HF patients." (PMID 40521364, 2025). "In cancer patients, decreased ALB levels are associated with systemic inflammation and malnutrition." (PMID 39941572, 2025). "The frail participants in these studies had evidence of inflammation, such as elevated ferritin levels, and evidence of malnutrition, such as low cholesterol and low serum albumin, which suggest frailty-associated low glycaemia." (PMID 40863223, 2025). "Second, the impact of nutritional status: a reduction in ALB levels is usually associated with malnutrition, which is an important promoting factor of renal dysfunction." (PMID 41426582, 2025). "GNRI, which assesses the risk of malnutrition in geriatric patients, is calculated using serum albumin and ideal body weight." (PMID 40407919, 2025). "The lower albumin levels observed in the hDFU group, coupled with its identification as a risk factor, highlight that malnutrition and systemic inflammation are key drivers of poor outcomes." (PMID 41384024, 2025). "The findings revealed that BMI, HGS, FFM, MUAC, and serum albumin levels are significant independent risk factors for malnutrition in this population." (PMID 40521364, 2025). "In HD patients, hypoalbuminemia has multifactorial causes, including reduced hepatic synthesis (malnutrition), increased catabolism and inflammatory activity, and dialysis-related amino-acid/albumin losses." (PMID 41552166, 2025). "Low albumin levels are usually associated with malnutrition, chronic diseases, and liver dysfunction." (PMID 41036272, 2025).
malnutrition (continued). "Research indicates that lower serum albumin levels are primarily linked to malnutrition and inflammatory responses, and are significantly associated with adverse clinical outcomes in patients with CHD." (PMID 41479660, 2025). "Hypoalbuminemia was defined as serum albumin levels <35 g/L, and malnutrition risk was assessed using the Mini Nutritional Assessment-Short Form (MNA-SF; score < 12)." (PMID 41536828, 2025). "Secondarily, malnutrition and inflammation, which are associated with reduced renal function and increased albumin turnover, can contribute to reduce albumin glycation rate." (PMID 40863134, 2025). "Elevated RDW, a component of RAR, reflects increased systemic inflammation and oxidative stress, while decreased albumin indicates malnutrition and reduced anti-inflammatory capacity—both strongly linked to cognitive dysfunction." (PMID 40568468, 2025). "Previous Japanese studies have shown that low masticatory ability is associated with low serum albumin levels (a marker of malnutrition) and that low protein intake is associated with frailty development." (PMID 39855881, 2025). "Handgrip strength (HGS) and albumin levels have been consistently linked to malnutrition in HF patients." (PMID 40521364, 2025). "Serum biochemical markers, including low albumin and elevated urea, were significantly associated with malnutrition, suggesting their potential utility as adjunctive indicators for early nutritional risk stratification." (PMID 40964588, 2025). "We separately analysed malnutrition-related complication risk based on tools that incorporate biological composite scores such as serum levels of albumin or total lymphocyte count." (PMID 41514593, 2025). "Low albumin levels reflect inflammation, malnutrition, or liver dysfunction, which are all associated with increased bleeding risk." (PMID 41227038, 2025). "Low albumin levels often indicate malnutrition, which can be due to dietary deficiencies, chronic diseases, or inflammation." (PMID 40520906, 2025). "Hypoalbuminemia, defined as serum albumin levels below 35 g/L, is a key biochemical marker not only for nutritional deficiency but also for systemic inflammation, liver dysfunction, and overall frailty in older adults." (PMID 41536828, 2025). "Nutritional deficiencies, such as vitamin D deficiency and low hemoglobin and albumin levels, which reflect overall health status, further compromise bone health." (PMID 40160472, 2025). "RAR was calculated using red blood cell distribution width and serum albumin measurements obtained from mobile examination centers, with higher values indicating greater systemic inflammation and nutritional deficiency." (PMID 42087928, 2025). "Low albumin levels indicate nutritional deficiency and systemic inflammation, which impair immune cell receptor mobility and signal transduction, thereby weakening the antitumor response and potentially promoting cancer progression." (PMID 40870429, 2025). "Low albumin levels indicate a higher risk of malnutrition, compromising immune function and increasing incision infection risk." (PMID 39193402, 2024). "Later during chemotherapy, a low serum albumin often can be attributed to well-known complications: malnutrition or hepatotoxicity quite commonly, renal or intestinal loss occasionally." (PMID 39305296, 2024). "Low albumin serum levels are indicative of malnutrition, which is associated with various clinical implications, such as lower quality of live, higher risk of therapy-associated side effects, reduced response to chemotherapy, and reduced cancer survival." (PMID 39409916, 2024). "Albumin, a key component of ALI, is influenced by inflammation and malnutrition, often leading to reduced albumin levels and weight loss." (PMID 39407934, 2024). "Lower serum albumin levels were significantly associated with increased mortality risk, reflecting systemic inflammation, malnutrition, and organ dysfunction commonly observed in ADHF patients." (PMID 39336426, 2024).
malnutrition (continued). "For the AMC and albumin, there was a reduction of 4.6% and 34.7%, respectively, in the risk of developing malnutrition-inflammation with an increase of 1 cm in the AMC and of 1 g/dL in albumin." (PMID 39284026, 2024). "Serum albumin levels are a significant indicator of malnutrition, and low levels have been shown to be closely associated with surgical site infections, other complications, and poor survival, regardless of the specific type of cancer." (PMID 38997737, 2024). "Another study in Italy identified dysphagia in HN cancer patients in 48% of cases, while 37.95% developed it throughout the treatment, as well as showing greater weight loss, malnutrition, and a reduction in albumin and white blood cell levels." (PMID 38732610, 2024). "The serum albumin level was a widely used marker of malnutrition, which has been demonstrated to be associated with postoperative complications and mortality following orthopedic procedures." (PMID 38840126, 2024). "Recent research indicates that reduced albumin levels correlate with systemic inflammation activation and heightened malnutrition risk, while also highlighting albumin’s capacity to shield tissues from inflammatory damage." (PMID 39036488, 2024). "Albumin, a well-known immunogenic protein, is often associated with malnutrition and widespread inflammation due to its low levels." (PMID 38750370, 2024). "Another widely used tool, the Geriatric Nutritional Risk Index, assesses malnutrition risk based on body mass index (BMI) and serum albumin levels." (PMID 39683392, 2024). "A decrease in albumin is generally indicative of disease, malnutrition, and blood loss, and in our study indicative of inflammatory response and body protein being used to repair sores." (PMID 39474311, 2024). "Low albumin levels and malnutrition in hip fracture patients are associated with physiological and metabolic changes." (PMID 38528491, 2024). "Prolonged inflammation and malnutrition also affect protein synthesis and metabolism, potentially causing decreased levels of substances such as hemoglobin, albumin, and creatinine." (PMID 39850334, 2024). "Recent research suggested that sleep disturbance was closely associated with a high risk of malnutrition in patients with liver cirrhosis, and albumin was a crucial factor in the assessment of malnutrition." (PMID 39430587, 2024). "As a traditional serum marker, albumin reflects nutritional status, which is closely related to malnutrition and significantly correlated with mortality risk in ACS patients." (PMID 39514617, 2024). "Recently, many studies have demonstrated that in addition to being an indicator of malnutrition, there also exists a robust association between albumin and severe infection." (PMID 39135753, 2024). "Malnutrition or enhanced vascular permeability can lead to low serum albumin levels, which are linked to heightened infection and BSI risks." (PMID 38983366, 2024). "Univariate cox regression analysis revealed that age ≥65 years, malnutrition (including BMI <18.5 kg/m2 or serum albumin <35 g/L) and hemoglobin <120 g/L were risk factors for ATB-DILI." (PMID 39108745, 2024). "Wang and colleagues found that lower serum fetuin-A levels in patients undergoing PD were associated with malnutrition, as assessed by serum albumin assay and subjective global assessment." (PMID 38402283, 2024). "These Asian studies have often found high rates of sarcopenia linked to lower physical activity levels, malnutrition, and metabolic factors, such as low serum albumin and hemoglobin, particularly among post-stroke patients." (PMID 39717682, 2024). "Decreases in albumin levels are associated with an inflammatory state and are observed in cancer, infections, malnutrition, liver illness, and kidney disease." (PMID 39339668, 2024).